IL6 (interleukin 6)
Diseases named in the same sentence as IL6 in open-access papers (continued):
Sharing a sentence is not in itself a finding about the gene and the disease.
tumor (continued). "Tumors may contain proinflammatory IL-6 that contributes to angiogenesis and cancer cachexia, as well as transforming growth factor beta (TGF-β), a product of regulatory CD4+ T cells (Tregs) which suppress effector immune cell function and contribute to tumor escape from host immune surveillance." (PMID 24955376, 2014). "Moreover, IL-17-producing αβ T cells stimulate the release of several cytokines (such as IL-6, IL-12, CXCL9, and CXCL10) by immune or cancer cells, leading to DC maturation or effector T cell recruitment to the tumor, and as a consequence, to an increase of the anti-tumor immunity." (PMID 25538706, 2014). "However, similar to ER PR data, the IL-6 data suggest that tamoxifen and aromatase inhibitors would likely target the largest tumor BCSC population represented by CD49f−CD24−(MM), but not the scarce stem/progenitor populations represented by CD49f+CD24+(PP), CD49f+CD24−(PM) or CD49f−CD24+(MP) cells." (PMID 25269750, 2014). "Consequently, given the current report that IL-6 promotes RET expression, the role of the GDNF–RET axis may be more relevant in those cancers characterised by an inflammatory response and an activated tumour microenvironment." (PMID 24467886, 2014). "In addition several studies have suggested that tumor-derived platelet-derived growth factor (PDGF), epidermal growth factor (EGF), vascular endothelial growth factor (VEGF), and interleukin-6 (IL-6) may be required for localization, integration and/or survival in tumors." (PMID 23744479, 2013). "However, the induced secretion of IL-6 by PGE2, as well as the basal levels of IL-6 secretion in these tissue derived fibroblasts both failed to associate with the tumor promoting abilities of these fibroblasts in vivo, or their ability to secrete PGE2 in vitro." (PMID 21957456, 2011). "Interestingly, IL-4, IL-6, IL-10 and GM-CSF have no regulatory effects on the expression of B7-H4 on tumor cells, indicating that the expression of B7-H4 in tumor cells may be functionally distinct and differently regulated compared with APCs." (PMID 22013483, 2011). "Since blocking Stat3 function in tumor cells is also known to activate adaptive immunity it may be that IL-6 induced Stat3 is in part responsible for no/low activation of NK cells in the co-cultures of NK cells and either HEp2 cells or UCLA-1 or HOK-16B tumors." (PMID 20661281, 2010). "In order to verify whether there was a gradient for VEGF, IL-6 and D-dimers between the afferent and efferent blood flow in a tumour we explicitely used samples from patients without distant metastasis (n=15) as VEGF, IL-6 and D-dimers produced by metastases could mask observed gradients." (PMID 12454774, 2002). "Many of the pathways discussed, such as the IL-6/STAT3-hepcidin crosstalk, are well-studied in vitro; however, there is a lack of direct evidence from human tumour samples of different CRC subtypes." (PMID 41153383, 2025). "Blocking IL-6 or IL-6R did not decrease viability nor migration of the cancer cells, whereas inhibiting macrophage migration inhibitory factor (MIF) did decrease tumor cell migration, but not viability." (PMID 40061210, 2025). "Calcitonin and IL-6 levels were above normal, consistent with advanced CCA, but not with a PCT/calcitonin-secreting tumor or systemic inflammation." (PMID 40419900, 2025). "Both tumour and nontumour cells in the tumour ecosystem produce factors such as HIF, VEGFA (Vascular Endothelial Growth Factor), IL-6, and IL-8, which stimulate endothelial cell proliferation and thus tumour vascularisation." (PMID 41009413, 2025). "The relative abundance of Fusobacterium nucleatum and the expression levels of cytokine genes (IL-1β, IL-6, IL-10, IL-17, TNF) were measured in tumor and adjacent normal tissues to assess their differential expression and potential associations." (PMID 41267807, 2025).
tumor (continued). "In particular, the effects of ADSC-EVs on the IL-6/STAT3 signaling pathway and microtubule organization—two key regulators of tumor growth and metastasis—have not been systematically explored." (PMID 41514893, 2025). "The absence of IL-6 signaling in macrophages triggered the secretion of CCL9, resulting in the recruitment of myeloid cells, specifically monocytes, to the tumor." (PMID 39653766, 2025). "In contrast to our findings, studies that employed the IL6 inhibitor, siltuximab, did not exhibit any cancer-inhibitory effects on LUSC tumor cell flank xenografts in nude mice." (PMID 41304808, 2025). "As for tumour Te‐EVs, small and large EVs from both HT29 and SW620 cells, but not CDD‐841‐CoN cells, significantly promoted TNF‐α and IL‐6 secretion by dTHP‐1 cells." (PMID 40326665, 2025). "In triple-negative breast cancer models, OC’s dual inhibition of IL-6/STAT3 and COX-2/mPGES-1 pathways reduced Th17/Treg cross-talk by 40%, diminishing IL-17A-driven PD-L1 expression on tumor cells while augmenting CD8+ T cell cytotoxicity." (PMID 40564985, 2025). "Treatment of mice with an IL-1β-neutralising antibody had no clear effect on primary tumor growth, but effectively inhibited CTSC-increased levels of circulating IL-6 and CCL3, as well as lung metastasis in mice." (PMID 41019086, 2025). "Notably, CD46 and TREM1 may collaboratively shape a tumor-promoting microenvironment: CD46 potentially mediates immunosuppression via T-cell regulation, while TREM1 drives sustained production of pro-inflammatory factors (e.g., TNF-α, IL-6) by amplifying NF-κB signaling." (PMID 41415031, 2025). "Despite not assessing IL-6 levels in CRT-NP treated tumors, the higher serum IL-6 levels and their negative correlation with tumor growth suggest an anti-tumor effect rather than a pro-tumoral one." (PMID 40386779, 2025). "In our study, we observed a slight increase in the expression of IL-17A, IL-6, and CXCL13 following PD-1 signaling activation, and no inhibitory effect on IFN-γ and TNF-α, which are downregulated in tumor T cells." (PMID 40825269, 2025). "This persistent inflammation induces immunosuppressive factors (TGF-β, IL-10, IL-6, VEGF) from immune and non-immune cells, which promote wound-healing and fibrosis while impairing anti-tumor immunity." (PMID 40227782, 2025). "Additionally, IL-6 levels can increase due to bacterial infections, which raises the possibility that elevated mortality might have resulted from infections rather than tumor progression." (PMID 38672257, 2024). "One day after HIFU therapy, no significant changes were detected in tumor cytokine levels; however, by Day 3, elevated levels of tumor IFN‐γ, TNF‐α, and IL‐6 were observed in the T‐MBs + HIFU group compared to the control group." (PMID 39431644, 2024). "On immunohistochemical analysis to investigate the localization of IL-6 in OSCC tissues, we found that most IL-6 expression was observed in stromal cells rather than in tumor cells." (PMID 38510850, 2024). "In orthotopic mouse models, blocking IL6 with a neutralizing antibody suppressed HPV − but not HPV + tumors, which was accompanied by increased tumor infiltration and proliferation of CD161+ NK cells." (PMID 38468260, 2024). "The results showed that siMUC1 tumour cells did not induce macrophage polarisation toward the M2 phenotype, and MUC1 knockdown led to a decrease in the cytokines ICAM and IL6." (PMID 38778448, 2024). "Surprisingly, we found that the positive rate of IL-6 was comparable between CCA tumor tissues and normal tissues, while the mean intensity was lower in the CCA tumor tissues (data not show)." (PMID 38881895, 2024). "IL-6, IL-1β and IL-23 can induce the expression of CD39 and CD73 in Th17 cells but have no direct effects on tumor growth." (PMID 39534095, 2024).
tumor (continued). "In addition to enhancing tumor-specific cytotoxic T cell responses, future immunotherapeutic approaches may need to focus on the immunosuppressive TME, including the role of CCR2+ monocytes, and the interplay with IFN-γ and IL-6 in HNSCC and the patients’ blood." (PMID 39882242, 2024). "It is noteworthy, however, that expression of IL6 and IL10 was similar between tumor and adjacent normal tissue (data not shown)." (PMID 38375204, 2023). "The expression levels of TNF-α, IL-6 and VEGF were also increased in patients with tumor invasion depth and serosal layer compared with patients without tumor invasion depth (all P < 0.001)." (PMID 37430251, 2023). "‐LPMs characterized in tumor‐bearing mice as F4/80high GATA6+ cells that proliferated during tumor progression.‐No expression of prototypical protumoral genes (IL10, TGFB and Retnla), but of proinflammatory genes (IL6, TNFA and IL1B)." (PMID 36658699, 2023). "However, the pharmacologic or genetic inhibition of STAT3 increases IL-6 expression in GBM cells and GSCs through unclear mechanisms, suggesting that therapeutically muting STAT3-dependent IL-6 induction may inadvertently suppress the tumor immune response to GBM." (PMID 37242454, 2023). "Within the tumor, CV8102 alone, and in combination with systemic anti-PD-1 treatment, induced similar amounts of IFN-α, IFN-β, IL-6, and TNF, while anti-PD-1 antibodies alone did not induce these cytokines." (PMID 36319717, 2023). "On the other hand, phagosome formation, the tumor microenvironment pathway, LPS/IL-1 mediated inhibition of RXR function, TREM1 signaling and IL-6 signaling were categorized with negative z-score." (PMID 37047308, 2023). "Local ULCA injection did not, however, increase levels of inflammatory cytokines IL-6 and tumor necrosis factor–α (TNF-α) in either tumor model." (PMID 36989357, 2023). "The progeny generated from GBM cells in the absence of IL-6, was homogeneous, demonstrating that IL-6 contributed to increased GBM heterogeneity and tumor formation." (PMID 36923251, 2023). "This conclusion is further supported by our observation that stimulation of HDMECs with the pro-angiogenic factors VEGF, EGF, bFGF, IL-6, and TNF-α, which are known to be secreted by tumor cells, has no influence on the expression of endothelial miR-186." (PMID 36845338, 2023). "Il-6 via the membrane receptor activates non-receptor tyrosine kinases including JAK2, which induce the JAK2/STAT3 cascade for angiogenesis and tumor enlargement because of regulating progression of the cell cycle." (PMID 37373969, 2023). "Multiple proinflammatory/immune recruitment (IL-1β, IL-6, IL-8, TNFα, IFNα, MIP-1β, CXCL12) and immune suppressive cytokines (IL-10) were found to be induced by tumor line-derived sEVs but not those derived from normal pancreatic cell lines." (PMID 37834100, 2023). "In fact, preliminary results of a gene expression analysis of fresh tumor tissue provided evidence that the mRNA levels of IL2, IFNG, IL6 and TNFA are increased in SGCT but not in NSGCT, which is in line with our cell culture data (unpublished results)." (PMID 37174085, 2023). "Other copy number reduced genes included SMAD4, HNF1B, and some gene loci that are not known to be tumor suppressor genes, such as KRAS, MYC, PIK3CA, and IL6." (PMID 36430324, 2022). "A reduction of luciferase signal was observed in all stable tumor cells treated with hyper-IL6, while no changes in luciferase signal was detected in any of the SMG1KD stable tumor cells expressing the luciferase NMD reporter." (PMID 36443756, 2022). "Serum levels of TNF-α, IL-6, IL-8, MCP-1, VEGF-A, and IL-1ra at baseline were significantly higher in SLE patients without skin involvement than in those with skin involvement." (PMID 35715525, 2022). "Consistently, tumor proliferation, apoptosis, and STAT3 phosphorylation, as well as gene expression of Ereg, IL-6, and IL-11, were not significantly altered in Villin:Cre-Phd2fl/fl mice as compared with the controls." (PMID 36509284, 2022).
tumor (continued). "Further analysis showed that the contents of IL-10 and TGF-β was significantly increased in tumor tissues, but there were no significant changes of TNF-α, IL-6, and IL-1β observed compared with the control group." (PMID 35646112, 2022). "Consistent with complete tumor elimination by 2-weeks of CAR T cell infusion with no sign of relapse, IL-6 and IL-8 dropped to below 2 pg/ml in CAR T cohorts with or without PEN-221 treatment." (PMID 36463361, 2022). "In this TPA-induced tumor model ERK5 was required to induce IL-1α, IL-1β, and COX-2, but not TNFα and IL-6 in epidermal keratinocytes." (PMID 34671021, 2021). "Pre-use of IL-6 and IL-1 receptor antagonists can prevent CRS without compromising tumor remission, but only IL-1 receptor blockade can prevent neurotoxicity." (PMID 34790576, 2021). "In this way, we observed a higher spleen mass (LW = W) and increased serum content of the pro-inflammatory cytokines IL-6 and TNF-α, which was not significantly different between both tumour-bearing groups (LW = W)." (PMID 34943780, 2021). "In most cancers, fibroblast polarization is triggered by tumor-derived factors such as TGF-β, PDGF, or IL-6, which exhibit only low or no expression in classical MCC cell lines and tumors (data not shown)." (PMID 33311552, 2021). "Positive and/or negative effects of adiponectin, IL-6, IL-8, MCP-1 and TIMP-1 on carcinogenesis, tumor development and metastasis, as well as on the efficacy of the treatment are described." (PMID 34572929, 2021). "Increased levels of IFN-γ and IFN-γ pathway genes are positive biomarkers of tumor response on ICI treatment and irAEs and IL-8, IL-6, and TGF-β are negative biomarkers." (PMID 35096992, 2021). "Medium or high expression of IL6, CASP3, ACTB and RAP1B was observed in 14/20 (~70%) lung metastasis tissues and in 11/20 (~55%) tumour tissues, whereas the expression was negative in the majority of adjacent non‐tumour tissues." (PMID 33759378, 2021). "We conclude that the growth promoting and anti-apoptotic mechanisms activated by IL-6, but not IL-6-mediated STAT3 activation, are critically involved in Eμ-myc driven tumor initiation and progression." (PMID 33651821, 2021). "Although we did not observe changes in human IL6 from the serum of mice harboring MDA-MB-231 tumor cells with or without MAFF expression, we still need to consider the effect of IL6 pathways through trans-signaling." (PMID 34262028, 2021). "Itacitinib can reduce the level of IL-6 released by macrophages and reduce cytokines production of CAR-T cells without affecting proliferation and anti-tumor activity of CAR-T cells." (PMID 34256851, 2021). "We generated Eμ-myc mice that either lacked the IL-6 gene, or lacked the STAT3 gene specifically in B cells to determine the role of the IL-6/JAK/STAT3 pathway in tumor development." (PMID 33651821, 2021). "Although IL-6 and TNF-α concentrations were not significantly different between our groups, their involvement in tumor growth should not be overlooked." (PMID 34439874, 2021). "However, our work shows that anti-IL-6 therapy alone has only modest efficacy and does not synergize with checkpoint inhibitors, suggesting that anti-IL-6 monotherapy may not fully reverse Mφ-mediated immunosuppression to activate anti-tumor immunity." (PMID 34103524, 2021). "Importantly, the tumor cells could significantly produce not only the ILs such as IL-6, IL-8, and IL-11, required for osteoclastogenesis, but also strengthen the expression of CXCR4 and CXCR7, establishing a “fertile soil” that accelerates tumor cells to adhere to bone matrix and thrive in bone." (PMID 36046435, 2021).
tumor (continued). "In nude mice bearing a human esophageal cancer cell line (YES-2) and in C26-bearing mice, oral supplementation with Coptidis rhizoma (containing the active component berberine) reduced tumor-derived IL-6 and BWL without changing food intake or tumor growth." (PMID 33255345, 2020). "LIF was actively secreted by C26 tumor cells, whereas TNF-α and IL-6 were not, and incubation of C2C12 myotubes with LIF was sufficient to induce atrophy." (PMID 33329046, 2020). "Additionally, MC-derived IL-6 and TGF-β1 could be considered a pro-tumorigenic threat, as these cytokines can directly contribute to the recruitment of myeloid-derived suppressor cells (MDSCs) and effector T cell polarization away from an anti-tumor Th1 toward a Th17 phenotype." (PMID 32098318, 2020). "IL-6, similar to TNF-α, promotes the transformation of noncancer cells into cancer stem cells while regulating the biological activity of tumor cells, leading to cell proliferation or distant metastasis." (PMID 32149121, 2020). "In direct contact co-culture system, IL-35 stimulation notably reduced the secretions of IFN-γ, IL-12p70, IL-6, IL-8, and TNF-α in CD8+ T cells purified from non-tumor and tumor site." (PMID 31134088, 2019). "Treatment with various cytokines, including IFN-γ, IL-2, IL-4, and IL-6, did not increase VISTA expression in tumour cells." (PMID 30382166, 2019). "In this report, intra-tumoral injection with STING ligand resulted in elevated levels of TNFα, IL6 and CCL2, but no significant increase in IFNγ within the Panc02 tumor microenvironment." (PMID 31036082, 2019). "Addition of TGF-β to tumor cell-N-MSC co-culture augmented MX2, BST2 and IL6 (right columns) but not ADAMTS12, LOXL2 GREM1 or CHI3L1 expression in N-MSCs." (PMID 29503225, 2018). "It has been shown that tumor-exosomes control the expansion of myeloid-derived suppressor cells through TLR2 and not TLR4, which leads to secretion of IL-6 and suppression of CD8+ T cells." (PMID 29867942, 2018). "Very interestingly, the combined blockade of IL-6 and PD-1/PD-L1 axe provides the synergistic effects not only on CD4+ Th1 response but also on the recruitment and function of CD8+ T cells in the tumor and its microenvironment." (PMID 30587227, 2018). "Median levels of proinflammatory cytokines (IL-6 and IL-8), HGF, and OPN tended to be lower at the end of the study in individuals exhibiting tumor response in comparison with subjects with no response." (PMID 30651923, 2018). "Potentially elevated secretion of IL6 and TNF by Snail-expressing cancer cells can therefore not explain the observed Dlk1-Dio3 locus repression in tumor-infiltrating immune cells." (PMID 30190790, 2018). "Among them, IL‐6 and TGFB1 were upregulated in the noncancer, tumor‐adjacent tissue of AAM, but for EAM, IL‐6 expression was increased in PCa tissue and TGFB1 was not differentially expressed." (PMID 29741809, 2018). "In order to liken the environment of a potential micrometastasis site, the tumor cells were cultured on top of a fibroblast monolayer in the presence of PBMCs with or without the augmented levels of CRP and IL-6 observed previously in patient sera." (PMID 30450100, 2018). "Results of our RNA‐sequencing data analysis pipeline revealed that IL‐6 was at significantly higher levels in the noncancer, tumor‐adjacent tissue of AAM relative to PCa from AAM and tumor‐adjacent tissue from EAM." (PMID 29741809, 2018). "Sera from peripheral blood of tumor-bearing hu-BLT mice exhibited increased secretion of IFN-γ, IL-10, and IL-6 as compared to the control mice with no tumor." (PMID 28424683, 2017). "For activation of STAT3 both EGFR mediated signaling as well as IL-6 signaling has been shown to be relevant and in NSCLC tumor cells JAK1 and not JAK2 was determined as the signal relaying kinase." (PMID 28402937, 2017).